IL1B (interleukin 1 beta)
Diseases named in the same sentence as IL1B in open-access papers (continued):
Sharing a sentence is not in itself a finding about the gene and the disease.
tumor (continued). "In LLC tumors, it has been shown that IL-1β release impairs the phenotype of tumor-infiltrating T cells and accumulation of intratumoral neutrophils and macrophages, resulting in an immunosuppressive TME." (PMID 37932814, 2023). "For example, TAMs induce IL–17 production through releasing IL–1β, the IL–17 can enhance neutrophils recruitment and promote tumor metastasis in breast cancer." (PMID 36845095, 2023). "We have previously demonstrated in contrast with LPS stimulation, which induces Il1b expression in both BMDM and MG cultures, organotypic tumor slices generated by Cdkn2a loss and PDGFB overexpression only induce Il1b expression in BMDM cocultures." (PMID 37733448, 2023). "Subsequently, CAF can alter the tumor microenvironment by secreting IL-1β, IL-6, and IL-8, thereby enhancing the migration of OS cells." (PMID 37990331, 2023). "Here, we proposed that IL‐1β involved in the interplay between tumor cells and TAMs elicited immunosuppression." (PMID 37009412, 2023). "In human breast carcinoma, IL-1α, IL-1β, and IL-1Rα were shown to be highly expressed and found to promote tumor progression." (PMID 37370720, 2023). "In this study, we found RT increased IL-1β protein expression at 3 h and 24 h post-RT in both tumor models." (PMID 38067390, 2023). "Deprivation of IL-1β through shRNA or neutralizing antibody restores anti-tumor immunity and improves the effect of anti-PD-1 therapy." (PMID 36932407, 2023). "Both Vγ6+ and Vγ4+ cells rapidly expand in response to tumor-derived factors, such as IL-1β and IL-23." (PMID 36480166, 2023). "By real-time RT-PCR analysis, the expression of Ifng, Tnf, and Il1β tended to be lower in the tumor of S100a4-Cre; Ext1f/f mice, and there was significant difference in Tnf expression." (PMID 36809261, 2023). "Although IL-1β is well recognized for its tumor-promoting function, its specific impact can vary across different cancers." (PMID 38066523, 2023). "Cytokines, such as IL-1β and TNFα, are primarily pro-inflammatory and play an important role in inflammation-driven tumor growth and progression and are found to be upregulated after radiotherapy in patients with GBM." (PMID 38003396, 2023). "Previous reports have shown that IL-8 and IL-1β, known to be proinflammatory cytokines, can promote cancer progression by supporting tumor proliferation, angiogenesis, and invasion." (PMID 36674955, 2023). "IL-1β in the TME increased PDGFB-driven GBM growth by increasing tumor-derived NF-κB, expression of monocyte chemoattractants, and increased infiltration of bone marrow–derived myeloid cells (BMDMs)." (PMID 37966120, 2023). "In the tumor-containing hemispheres, we detected high levels of active IL-1β as a readout for inflammasome activation." (PMID 37749707, 2023). "Based on previously reported studies, it has been documented that IL1B, CXCL1, CDK6, and IGFBP3 were closely associated with tumor radiosensitivity." (PMID 37468464, 2023). "We also observed that the depletion of IL‐1β cytokine and type I IFNs abrogated tumor regression induced by the Arf1‐ablated tumor cells in mice." (PMID 37786300, 2023). "This L1CAM pathway leads to the activation of the constitutive nuclear factor NF-κB pathway by enhancing the IL1β expression, which further promotes cell motility, tumor cell growth, and cancer metastasis." (PMID 37893107, 2023). "IL‐1β levels in tumor tissues were negatively correlated with overall survival in patients with other two types of cancers, which was observed with Gene Expression Omnibus datasets." (PMID 37009412, 2023). "The M1 macrophages secrete pro-inflammatory cytokines TNF-α, IFN-γ, IL-1β and IL-8 and exert pro-inflammatory and anti-tumor functions." (PMID 36845095, 2023). "In examining select cytokines in the core and edge regions, we observed an elevation in TNF-α, IL-1β, and IL-6 in the edge compared to the tumor core." (PMID 37752585, 2023).
tumor (continued). "Further in vitro experiments revealed that IFNγ + IL1β/TNFα increased the elongation and migration of treated tumor cells." (PMID 37169743, 2023). "In contrast, although Nigericin causes initial tumor cell death in tumor cell lines with strong NLRP3 activation and IL-1β and IL-18 production, cells recover and tumors remain active." (PMID 37715239, 2023). "Genetic Il1b ablation in the TME significantly prolonged the survival of tumor-bearing mice, recapitulating the results of the RCAS/Ntv-a system and suggesting that this beneficial effect of Il1b loss is a TME-driven effect." (PMID 37733448, 2023). "K3ZrF7:Yb/Er upconversion nanoparticles (ZrNPs), a pyroptosis inducer, induces tumor cell pyroptosis through the GSDMD/IL-1β pathway, leading to cell lysis." (PMID 37705746, 2023). "For example, colorectal CSC-derived exosomal RNAs induced the expression of IL-1β through a pattern recognition-NF-κB signaling axis to sustain neutrophil survival and elevate tumor formation." (PMID 37789353, 2023). "TME, known as an important prognostic marker in cancer patients, features with various pro-inflammatory cytokines including tumor necrosis factor-α (TNF-α), IL-1β and IL-6 to build a tumor-supportive microenvironment to escape immune surveillance." (PMID 37047623, 2023). "The immune responses induced by bacterial cells colonizing in tumors were evaluated by measuring the levels of the proinflammatory cytokines, including IFN-γ, TNF-α, and IL-1β, in the tumor tissues." (PMID 36832032, 2023). "Administration of IL-1β increased the population size and functionality of adoptively transferred T cells within the tumor." (PMID 36742298, 2023). "Although blocking macrophage-derived IL-1β retards tumor growth during paclitaxel therapy, tumor metastasis and M2-like polarization of TAMs are enhanced indicating IL-1β to be a double-edged sword." (PMID 36932407, 2023). "Taken together, our results demonstrated that tumor-induced microbiota alteration impaired STC in the CA1 neuron by promoting IL-1β production in vivo." (PMID 37400621, 2023). "Macrophages release IL-1β indicative of inflammasome activation after stimulation with LPS and tumor-CM, which is AIM2 dependent." (PMID 37449203, 2023). "Positive anti-tumor effects of recombinant IL-1β have been shown, and blockade of IL-1β by treatment with IL-1 receptor antagonist (IL-1Ra) impaired a cancer response by reducing Th1 and tumoricidal macrophage activation." (PMID 37461742, 2023). "Migration of innate immune cells including macrophages, dendritic cells, and neutrophils are enhanced by expression of pro-inflammatory cytokines such as TNF-α, IL-1β, and IL-18 to result in overall tumor regression." (PMID 37514190, 2023). "Among cytokines, βA most significantly increased the expression of Il1b, Il18 Il33, and Il15, both within tumor cells and fibroblasts." (PMID 38304252, 2023). "Anakinra inhibited the expression of IL-1β in tumor cells and PBMCs of GBM, inhibited the proliferation and migration of tumor cells, and reduced inflammatory signals." (PMID 37723542, 2023). "GSDMD-mediated pyroptosis accompanies the release of the pro-inflammatory cytokine IL-1β,26,39 which supports the tumor-specific T helper 1 cell-mediated immune response against cancer." (PMID 36699618, 2023). "M1 macrophages mainly induce the production of pro-inflammatory cytokines such as TNF-α, IL-1β, IL-6, and IL-12, which are conducive to anti-tumor effects." (PMID 37758759, 2023). "Experimental evidence across most cancer types, supports a tumor-promoting role for IL1β [reviewed] making IL1β a target with clear therapeutic potential." (PMID 37065483, 2023). "This cascade further potentiates IL-1β production via TAMs and triggers inflammasomes to promote further tumor growth." (PMID 37511306, 2023). "The action of the cytokine IL-1β in the tumor microenvironment (TME) is mediated by the activation of inflammasome complexes." (PMID 37577033, 2023).
tumor (continued). "The IL1B gene, a target of HIF-1, has been implicated in tumor growth, metastasis, invasiveness and angiogenesis, partially by regulating other pro-inflammatory cytokine and growth factor secretion." (PMID 37542119, 2023). "MCP levels were elevated in PDGFB-driven GBM compared with normal brain, and treatment of these tumor cells with IL-1β increased MCP expression concomitant with increased NF-κB activation via phosphorylation." (PMID 37966120, 2023). "We next investigated the source of increased IL-1β in KRASMUT cancers, since both the host immune and tumor cells are capable of IL-1β production." (PMID 36980752, 2023). "Recent investigations have demonstrated that the tumor exosomes activate the NFkB pathway and enhance the expression of pro-inflammatory cytokines, including IL-8 and IL-1β, which boost macrophage polarization into the M2 phenotype." (PMID 37892995, 2023). "IL-1β treatment significantly increased MMP9 expression in mouse tumor tissues on the basis of the results of qPCR (9.57 ± 0.26 vs. 1.08 ± 0.44, P < 0.0001) and western blotting (1.13 ± 0.07 vs. 0.21 ± 0.04, P < 0.0001)." (PMID 37106440, 2023). "Apart from this, JNK has activated the inflammatory lung environment to support tumor development by regulating cytokines including IL-1β and TNF-α." (PMID 37259369, 2023). "We also examined the effect of ADT in combination with anti‐IL‐1β antibody and anti‐PD‐1 antibody in another Pbsn‐Cre4; Ptenfl/fl; Hi‐Myc organoid‐derived tumor model." (PMID 37092583, 2023). "Inflammasomes can regulate immune cells and inflammatory factors, such as IL-1β and IL-18, to inhibit tumor growth, differentiation, and metastasis." (PMID 37705746, 2023). "DEX treatment also decreased the levels of pro-inflammatory cytokines, including IL-1β, TNFα, IL-10, and IL-18, which are major tumor growth promoters." (PMID 37528154, 2023). "The connection between inflammasome complexes and the immune system is represented by the secretion and maturation of pro-inflammatory IL-1β, which activates the NF-kB signaling pathway and angiogenic signals, leading to tumor development." (PMID 36834660, 2023). "of human IL-1β promotes gastric tumorigenesis in transgenic mice, whereas a reduced tumor volume has been observed in IL-18-silenced nude mice." (PMID 37891577, 2023). "Through exploring the interaction between PA tumor cells and osteoclasts, we have shown that the release of inflammatory factors, mainly IL-1β, of PAs drives monocyte–osteoclast differentiation and aggravates the progression of bone invasion." (PMID 36900414, 2023). "Our observations suggest that tumor cells induce and maintain the autocrine IL-1β activation loop in CAFs, which altogether favors tumor progression." (PMID 37460545, 2023). "Our results now suggest that MAPK signaling is a potential new therapeutic target to inhibit pathogenic expression of PD-L1 on tumor cells induced by combined stimulation with IFN-γ and IL-1β." (PMID 37441079, 2023). "In the tumor microenvironment, there are different levels of proinflammatory cytokines such as IL-1β, IL-6, IL-8, and TNF-α." (PMID 38137862, 2023). "In tumor cells, IL-1β can promote NF-kB pathway activation, tumor cell proliferation, and epithelial-mesenchymal transition activity in a manner that contributes to tumor progression." (PMID 37885032, 2023). "Within a tumor, IL-1β is produced and secreted by various types of cells such as those of the immune system, fibroblasts, or tumor cells." (PMID 38137888, 2023). "Studies have shown that the expression of IL-1β in tumors is higher than that in normal tissues, and this factor can promote the growth, invasion and metastasis of tumor cells, which is negatively correlated with prognosis." (PMID 36605484, 2023).
tumor (continued). "Anti-IL-1β therapy is shown to decrease metastasis, invasiveness, inflammation-mediated immunosuppression concomitantly with increased anti-tumor immunity response." (PMID 36835413, 2023). "DAMPs activate inflammasomes that are able to coordinate with TLR4 signal to induce IL-1β secretion and adaptive anti-tumor immunity in DCs." (PMID 36932407, 2023). "Hub gene IL-1B is produced and secreted by a range of tumor cell types, including immune cells, fibroblasts, and cancer cells." (PMID 37894904, 2023). "The addition of an IL-1-inhibiting antibody to the CAF pre-treatment step resulted in an inhibition of this effect, demonstrating that the CAFs induced tumor spheroid growth by secreting IL-1β." (PMID 37460545, 2023). "HIF-1α, coupled with the expression of target genes encoding glycolytic enzymes and the pro-inflammatory cytokine IL-1β, can block tumor growth and survival and exacerbate inflammation." (PMID 37492564, 2023). "The immunosuppressive role of IL‐1β was due to its upregulation of immune‐suppressing genes in different tumor cells, with CD274 being the most consistently upregulated gene." (PMID 37009412, 2023). "Both IL‐1α and IL‐1β promote tumor angiogenesis and invasion, but IL‐1β has a more prominent role in these processes." (PMID 37547175, 2023). "In comparison with non‐treatment SKOV3, IL‐1β‐primed SKOV3 tumor cells were more tolerant when directly co‐cultured with NY‐ESO‐1 CAR‐T cells." (PMID 37009412, 2023). "In another instance, Salmonella mutant strain ΔppGpp enhanced production of TNF- α and IL-1β by macrophages and dendritic cells within tumor cells and induced tumor cell apoptosis." (PMID 38090593, 2023). "Our discovery of high levels of the pro-inflammatory cytokines TNFα, IL-1β, and IL-6 led us to test if these cytokines aided in tumor destruction or promotion." (PMID 37461742, 2023). "Scorch death, as a form of inflammatory cell death, releases large amounts of inflammatory factors such as IL-1β and IL-18, which are released into the tumor microenvironment." (PMID 37542283, 2023). "Pre-clinical work has found that tumor cell IL1β drives TAM recruitment, immunosuppression, and tumor progression in TNBC." (PMID 37065483, 2023). "The synergistic antitumour effects was also confirmed based on the suppression of IL-1β activation and NF-κB phosphorylation in tumours." (PMID 37037815, 2023). "IL-1β, a pro-inflammatory cytokine, is known to promote angiogenesis and invasiveness of tumor cells." (PMID 37373987, 2023). "We show that tumor conditioned media (CM) can induce IL-1β production, indicative of inflammasome activation in primed macrophages." (PMID 37449203, 2023). "How interactions among GBM cells of different genotypes or transcriptional subtypes influence tumor growth and the prevalence and function of TAMs, including through IL-1β, remains to be further investigated." (PMID 37966120, 2023). "Previous studies have shown that CAFs respond to cytokines (TNF, IL-1β) in the tumor microenvironment to drive their proinflammatory activation." (PMID 38203319, 2023). "Specifically, IL‐1β released from TAMs was triggered by lactate, the anaerobic metabolite of tumor cells, in an inflammasome activation‐dependent manner." (PMID 37009412, 2023). "The secretion of IL-1β by tumor cells emerges as a contributing factor to the disruption of REM sleep and subsequent sleep deprivation by affecting the levels of various sleep-related neurotransmitters, including prostaglandins, nitric oxide, GABA, and others." (PMID 38105184, 2023). "When stimulated by pro-inflammatory cytokines such as IL-1α, IL-1β, and tumor necrosis factor α, CAFs tend to shift towards a senescent state, inhibiting tumor cell apoptosis and promoting tumor cell dissemination." (PMID 38013358, 2023). "IL-1b (100 ng per mouse; in tumor; twice a week; for 2 weeks) significantly reversed the growth of subcutaneous INHBB-knockdown MGC-803 xenografts." (PMID 37858201, 2023).
tumor (continued). "OMVs trigger caspase activation, ultimately leading to the production of IL-1β and IL-8, proinflammatory cytokines that result in inflammation of the tumor cells, which constitutes a particularly promising attribute to exploit for therapeutic delivery." (PMID 37514190, 2023). "As CCL2 functions as the most critical chemokine in the recruitment of Mφ to tumor sites, we analyzed transcriptome data from IL‐1β‐treated A549/ U87MG cells and found that CCL2 was one of the most highly upregulated chemokine genes." (PMID 37009412, 2023). "IL-1β produced by NLRP3 IAP in dendritic cells is required to prime IFN-γ–producing CD8 T cells by dying tumor cells." (PMID 36742298, 2023). "We found that TCIPA triggers the recruitment of tumor-associated macrophages (TAMs) to lung metastases by secreting B16 cell-educated platelet-derived chemokines such as CCL2, SDF-1, and IL-1β." (PMID 37872588, 2023). "IL-1β and coculture of tumor cells with macrophages enhances the proliferation of tumor cells which is AIM2 and Casp1/11 dependent." (PMID 37449203, 2023). "Using these murine PDGFB-driven (PDGFB mGBM) and Nf1-silenced (Nf1 mGBM) GBM models that show differential myeloid recruitment, we investigated how IL-1α and IL-1β individually contribute to tumor development in vitro and in vivo." (PMID 37733448, 2023). "The proinflammatory subtype of macrophages (M1) are producers of the cytokines IL-1β and IFNγ; however, further phenotyping of cell surface markers would be required to determine if the macrophages in the treated tumor populations were of an M1 phenotype." (PMID 37893110, 2023). "Il1b expression also increased in DCs and MonoMacs, whereas βA-expressing tumor cells showed also elevated levels of Il16 mRNA." (PMID 38304252, 2023). "We also elucidated the inflammation levels in the tumor tissues of each group and observed that the mRNA expression of IL-1β and IL-8 was increased but that of IL-10 decreased after LINC00174 overexpression." (PMID 37448887, 2023). "In adipocytes, NLRC4 inflammasomes induce tumor infiltration into myeloid cells, and IL-1β promotes vascular endothelial growth factor A (VEGFA) secretion and angiogenesis, thereby driving disease progression." (PMID 37020871, 2023). "The blockade of IL‐1β not only impaired PD‐L1 expression in tumor cells but also decreased in vivo Mφ infiltration." (PMID 37009412, 2023). "Consistent with the findings obtained from tumor-bearing lung tissues, NR1D1 deficiency led to increased mRNA expression of Nlrp3, Il1β, and Il18 in AM, as well as increased protein expression of NLRP3 and cleaved caspase-1 in both AM and normal lung tissues." (PMID 37524704, 2023). "IL-1β was a multipotent cytokine, a critical factor in initiating immune responses, and a hub mediator of the inflammatory tumor microenvironment." (PMID 37996554, 2023). "that trigger effective IL-1β/TNF-α-mediated immune responses in the tumor leading to tumor regression are preferred over E. coli." (PMID 36900277, 2023). "With RNA‐sequencing, IL‐1β enhanced a range of immune inhibitory molecules expression on tumor cells, including CD274, PDCD1LG2, and IDO1." (PMID 37009412, 2023). "NLRP3/IL‐1β overexpressing tumor cells also attracted polymorphonuclear myeloid‐derived suppressor cells." (PMID 38116060, 2023). "Firstly, macrophages exhibited a significant decrease in IL-1β release when treated with DNA-RNA hybrid-depleted tumor conditioned media." (PMID 37449203, 2023). "miRNAs targeting IL1B, a cytokine promoting immune suppression and tumor proliferation through tumor stroma interaction, were downregulated in PDAC plasma as well." (PMID 37007745, 2023). "IL-1B is an inflammatory chemokine expressed via the NF-κB (gene Nfkbia) signaling pathway that plays important roles in tumor initiation and metastasis." (PMID 37994159, 2023).